RNU6ATAC19P (RNA, U6atac small nuclear 19, pseudogene)
Gene: Small nuclear RNA gene on chromosome 2 (181,738,606 to 181,738,715, forward strand). Ensembl gene ENSG00000221023.
Homologues: Orthologues: chimpanzee RNU6ATAC19P (100% identical), mouse Gm25541 (81% identical), rat LOC120102097 (80% identical), rat LOC120097629 (73% identical), rat LOC120103354 (66% identical). Paralogues in human: RNU6ATAC (79% identical), RNU6ATAC6P (75% identical), RNU6ATAC27P (74% identical), RNU6ATAC21P (72% identical), RNU6ATAC7P (72% identical), RNU6ATAC41P (71% identical), RNU6ATAC8P (68% identical), RNU6ATAC39P (53% identical), RNU6ATAC22P (44% identical).